CSF1R (colony stimulating factor 1 receptor)
Diseases named in the same sentence as CSF1R in open-access papers (continued):
Sharing a sentence is not in itself a finding about the gene and the disease.
cancer (continued). "Liver enzymes were elevated upon PLX5622 treatment, consistent with clinical studies using CSF1R inhibitors in cancer patients, most likely as a consequence of decreased liver enzyme clearance by Kupffer cells." (PMID 37792013, 2023). "CSF1R kinase inhibitors and anti-CSF1R antibodies have been evaluated for therapeutic intervention in diseases where macrophages contribute to pathology, e.g., neurodegenerative disease, cancer, inflammation, and fibrosis [123•, 124]." (PMID 36197652, 2022). "Mounting studies have shown that CSF-1R overexpression leads to poor prognosis in various cancer types." (PMID 35444953, 2022). "The use of CSF1R inhibitors in cancer therapy is currently of great interest, with various therapeutic approaches targeting its ligand or receptor in clinical development." (PMID 35530327, 2022). "Increased expression of CSF1 and CSF1R were found to be specific to cancer regions in high-grade PCa (e.g., Gleason 9) in comparison to normal adjacent regions (n = 3 patients)." (PMID 36209194, 2022). "For example, LAMP2 gene expression levels were positively correlated with those of immunoinhibitors CD274 (PD-L1) and CSF1R in a variety of cancers." (PMID 35530327, 2022). "Alkylating agents (like cisplatin and carboplatin) inhibit DNA replication from causing cancer cell death, wherein such dying cancer cells express more CSF1, thereby attracting large numbers of CSF1R+ TAMs (M2-like)." (PMID 36497148, 2022). "We link the transdifferentiation to a small subset of CSF1R+ Pax5Low cells within BM pre-B and immature B cells responding to cancer-secreted M-CSF with downregulation of the transcription factor Pax5 via CSF1R signaling." (PMID 36104343, 2022). "The anti-tumorigenic potential of CSF1R inhibition is documented in various cancers, and thus a variety of anti-CSF1R molecules (monoclonal antibodies and small-molecule inhibitors) were developed." (PMID 35267626, 2022). "Pexidartinib is an orally administered small-molecule tyrosine kinase inhibitor that selectively inhibits CSF1R, and is currently being assessed for other types of cancer." (PMID 35311155, 2022). "In mice with 4T1 cancer, CSF1R+CD93+CD19+ BMBP were markedly reduced in BM but increased in the spleen, consistent with their cancer-induced emigration from BM." (PMID 36104343, 2022). "In this study, we document the characterization of the Axl/Mer/CSF1R inhibitor, Q702, in cancer immunotherapy." (PMID 36230744, 2022). "In this process, CSF-1 secretion by cancer cells mediates macrophage chemotaxis into the neural niche by activation of CSF-1 receptor (CSF-1R)." (PMID 35455973, 2022). "The intratumoural presence of CSF1R-positive macrophages correlates with poor survival in various cancer types." (PMID 35887121, 2022). "Administration of the humanized anti-CSF1R antibody AMG820 in cancer patients produced sustained elevation of circulating CSF1 and ablation of dermal macrophages." (PMID 36197652, 2022). "Given that PAX5 is the key pro-B-cell factor that represses Csf1r and other myeloid lineage-specific genes, we reasoned that cancer decreases levels of this transcription factor using M-CSF." (PMID 36104343, 2022). "In our study we described the changes to CSF-1R expression with aging and cancer in monocytes and macrophages, however the presence of CSF-1 affects surface and intracellular expression of CSF-1R." (PMID 35821822, 2022). "We propose that cancer primarily targets a small subset of CSF1R+Pax5Low pre-B cells and iB cells recently emigrated from BM." (PMID 36104343, 2022). "Therapeutic blockade of CSF-1R or the inhibition of its signal transduction have shown protective activity across different murine cancer models, and are investigated in ongoing clinical trials." (PMID 36561751, 2022). "Here, we report that cancers transdifferentiate the bona fide BM B-cell precursors, including Csf1R+Pax5Low pre-B and immature IgM+ B cells, into TAM (termed B-MF) using M-CSF." (PMID 36104343, 2022).
cancer (continued). "This reexepression in adult cancer cells suggested a potential role of CSF-1R in prostate carcinogenesis." (PMID 36555673, 2022). "This suggests that spp1/osteopontin is one example of CSF-1-responsive genes shared between myelomonocytic lineage and carcinoma cells expressing CSF-1R." (PMID 36555673, 2022). "These notable differences warrant further research to decipher the specific substrates of CSF-1R in carcinoma." (PMID 36555673, 2022). "Understanding the signaling mechanism of CSF-1 and CSF-1R in cancer and other diseases and taking appropriate measures to block CSF-1/CSF-1R signaling is a promising new immunotherapy with potential for future clinical application." (PMID 34729112, 2021). "Increasing research has shown that CSF-1 and CSF-1R are expressed in malignant tumors of the digestive tract and can promote the growth, migration and invasion of tumors." (PMID 34729112, 2021). "For example, mRNA expression of PD‐L1 is significantly correlated with CSF1R in 26 cancers (median Rs = 0.48)." (PMID 33510997, 2021). "CSF-1R blocking agents are also being investigated for synergistic effects with current cancer therapeutics in preclinical studies." (PMID 34988021, 2021). "One of the most promising therapeutic targets for the repolarization of TAMs for cancer treatment is a blockade of the colony-stimulating factor (CSF)-1/colony-stimulating factor-1 receptor (CSF-1R) pathway." (PMID 34205330, 2021). "For example, colony stimulating factor 1 receptor (CSF1R), a Sunitinib target, correlated with macrophage in 33 cancers (median Rs = 0.80), MDSC in 33 cancers (median Rs = 0.84), and Tregs in 33 cancers (median Rs = 0.83)." (PMID 33510997, 2021). "Blockade of colony-stimulating factor-1 (CSF-1) or its receptor CSF-1R represents a selective approach to manipulate macrophages in cancer patients and some studies have explored this new therapeutic axis in some hematologic malignancies." (PMID 33731849, 2021). "Blocking CSF-1R with antibodies can reduce the activation of CSF-1 and prevent the proliferation and metastasis of malignant tumors." (PMID 34729112, 2021). "Previous studies have suggested expression of CSF1R on cancer cells in OCs, however, our findings clearly indicate that the expression is largely restricted to TAMs." (PMID 34220848, 2021). "Recently, IL-34 has been identified as a ligand for CSF1R that is involved in promoting disease progression in various conditions ranging from inflammation to cancer." (PMID 33800170, 2021). "CSF-1R is overexpressed in many cancers and cancer-related macrophages and is therefore used as a drug target for cancer and inflammatory diseases." (PMID 34729112, 2021). "CSF-1R is a promising target to address TAMs therapeutically, as high expression of CSF-1 or CSF-1R predicts cancer progression and mortality." (PMID 33968034, 2021). "Inhibition of TAM proliferation and survival through CSF1R blockade has been widely explored as a cancer immunotherapy." (PMID 33511454, 2021). "Targeting CSF1/CSF1R for M2 macrophage reprogramming has been widely performed in clinical trials for cancer therapy." (PMID 34248982, 2021). "Several CSF-1R blocking antibodies were also developed and investigated in clinical trials as an anti-cancer therapy." (PMID 34988021, 2021). "Targeted inhibition of the CSF-1/CSF-1R signal axis has broad application prospects in cancer immunotherapy." (PMID 34729112, 2021). "At present, multiple clinical trials are being designed and conducted to test the clinical efficacies of CSF‐1R inhibitors on cancer inhibition." (PMID 33463063, 2021). "Signaling governed by CSF-1R in TAMs has been shown to promote immunosuppressive as well as invasive/metastatic behavior in malignant tumors." (PMID 34843542, 2021).
cancer (continued). "When analyzed for regulatory T cells, the cases with concurrent low CSF-1R+ carcinoma cells and low FOXP3 iTILs exhibit the best outcome (HR 0.71, 95% CI 0.60–0.86; p = 0.001)." (PMID 34830923, 2021). "Our findings in this regard are important, as using immunohistochemistry, we were able to distinguish between carcinoma cell and macrophage cell CSF-1R expression." (PMID 34830923, 2021). "It has been shown that the carcinoma cells actively contribute to compensatory mechanisms that promote the survival of macrophages following CSF-1R inhibitor therapy." (PMID 34830923, 2021). "We next performed a prespecified subgroup analysis to investigate the prognostic impact of CSF-1R+ carcinoma cells in cases stratified by ER status." (PMID 34830923, 2021). "High carcinoma CSF-1R correlated with grade 3 tumors >2 cm, hormone receptor negativity, high Ki67, immune checkpoint biomarkers, and macrophages expressing CSF-1R and CD163." (PMID 34830923, 2021). "The more widely held view is that the CSF1R signaling or CSF1R-dependent microglial signaling suppression would perform protective function for several diseases including cancer therapy, neurodegenerative disease, and ischemia stroke." (PMID 32908485, 2020). "Emerging data address the potential mechanism by which CSF1R blockade has been ineffective in inflammation and cancer." (PMID 32801364, 2020). "Presumably, the reduction of CSF-1R expression in THP-1 cells led to a decreased response of the cells to CSF-1 secreted by cancer cells." (PMID 33156861, 2020). "Various CSF1R inhibitors were developed and used alone or in combination with other agents for different type of cancers." (PMID 33343560, 2020). "CSF1R inhibitors are currently under clinical trials to determine their safety and efficacy in the context of cancer treatments." (PMID 32429943, 2020). "We discuss the potential therapeutic effects of targeting CSF1R or its ligands on bone diseases, neurological disease, and cancer." (PMID 32801364, 2020). "Therapies targeted against the TAMs by inhibiting colony stimulating factor‐1 receptor (CSF‐1R) have emerged as a promising approach for cancer treatment." (PMID 33037771, 2020). "Based on these preclinical studies, several ongoing clinical studies are currently exploring the efficacy of targeting TAMs in cancer patients using anti-CSF1R antibodies in combination with chemotherapy or immunotherapy." (PMID 33276524, 2020). "They explore the links between the CSF1R-mediated signaling pathway and diseases such as cancer and neurodegeneration." (PMID 32801364, 2020). "Pexidartinib (PLX3397), JNJ-40346527, and PLX7486 are tyrosine kinase inhibitors of CSF-1R signaling that are currently being used in phase I–III clinical trials for different types of cancers." (PMID 32326073, 2020). "Depletion of Stat3 in CSF1R expressing cells in mice resulted in drastic inflammatory response of the intestine and malignant tumor formation." (PMID 33343560, 2020). "Depletion of TAMs by clodronate-loaded liposomes or a CSF-1R inhibitor augmented the effect of anti-cancer treatment." (PMID 30770776, 2019). "3D185 inhibited FGFR1-, FGFR2-, FGFR3-, and CSF-1R-mediated cancer cell proliferation, with IC50 values ranging from 0.9 to 36.8 nM." (PMID 31438996, 2019). "Next, the impact of 3D185 on FGFR- and CSF-1R-mediated cancer cell proliferation was explored, and 11 FGFR- or CSF-1R-dependent cancer cell lines were chosen." (PMID 31438996, 2019). "Inhibition of CXCR2, which is the receptor for most of the up-regulated CAF-secreted cytokines in response to CSF-1R inhibition, alongside with CSF-1R resulted in significant delay in cancer progression." (PMID 31331034, 2019). "Since CSF-1R is overexpressed in many tumors and at sites of inflammation, CSF-1R inhibitors seem to be an attractive therapeutic strategy for cancer as well as autoimmune and inflammatory diseases." (PMID 31216762, 2019).
cancer (continued). "We found Group A and Group B cancers had a higher number of CSF1R-positive cells (median = 65; 95% CI: 51–128 and median = 39; 95% CI: 21–65, respectively) than Group C (16; 8–23; p < 0.0001 and p = 0.0036, respectively)." (PMID 31431617, 2019). "The pharmacological blockade of CSF1R signaling has also been proposed as a means to modulate certain cancers, and inflammatory, autoimmune and bone diseases." (PMID 29593242, 2018). "Several studies using CSF1-R inhibitors have proved their efficacy by inhibiting altenative-M2 markers on BMDM in several primary cancers, although its potential role in BM is still to be elucidated." (PMID 30483064, 2018). "To address the role of CSF-1R in cancer cell migration, we pretreated cells with a CSF-1R blocking antibody." (PMID 29796177, 2018). "To this end, we blocked CSF1R only during early asymptomatic stages of cancer, starting at age week 18, and stopped as soon as tumors became palpable (size <3 mm in diameter)." (PMID 29295986, 2018). "In contrast to IFN-based therapy, colony-stimulating factor 1 receptor (CSF1R) has only recently emerged as a cancer drug target." (PMID 29946544, 2018). "Colony stimulating factor 1 receptor (CSF-1R) regulates the monocyte/macrophage system, which is an essential component of cancer development." (PMID 29228668, 2017). "Various small-molecule kinase inhibitors and antibodies directed against CSF1 or CSF1R were combined with chemotherapies, irradiation, anti-angiogenic or cancer immunotherapies using immunocompetent and immunodeficient mouse models." (PMID 28716061, 2017). "Based on the data that most cancers are populated by M2 Mφ, preclinical and clinical studies in several solid tumor types are designed using CSF-1R inhibitors or blocking monoclonal antibodies to reduce the presence of TAM." (PMID 28202073, 2017). "CSF1R is important for the differentiation and survival of macrophages and therefore is under investigation as a target in cancer therapy." (PMID 26666269, 2016). "The therapeutic potential of CSF1R inhibitors has been suggested in inflammatory diseases, autoimmune disorders, bone disease and cancer (Burns and Wilks, 2011;Pyontecket al., 2013)." (PMID 26747862, 2016). "To determine the effect of inhibition of CSF-1 and CCL2 signalling on cancer cells we utilised the small molecule inhibitors of CSF-1R (GW2580) and CCR2 (RS102895)." (PMID 26174804, 2015). "This indicates that by blocking CSF-1R signalling, an inflammatory phenotype can be obtained, even in the presence of cancer cells." (PMID 26174804, 2015). "TAMs express monocyte colony stimulating factor receptor (M-CSFR, also known as CSF-1R or cFMS), which binds monocyte colony stimulating factor (M-CSF, also known as CSF-1) secreted by cancer cells." (PMID 26243145, 2015). "Based on these findings we can conclude that the used CSF-1 dose mimicked the presence of macrophages in cancer cells environment regarding the CSF-1R signaling." (PMID 23561040, 2013). "Our gene expression analysis also revealed up-regulation of CSF-2 (GM-CSF) in macrophages grown as co-culture with cancer cells and CSF-2, CSF-3 and CSF1R up-regulation in cancer cells grown together with macrophages." (PMID 22353646, 2012). "The expression of CSF-1R antigen was significantly higher (p < 0.05) in all the cancer cell lines after co-culturing with macrophages." (PMID 22353646, 2012). "Our confocal imaging and IHC examination has proven that under co-culture conditions expression of macrophages markers (CD14, CD64, CSF1R) in almost all of the cancer cells was initiated." (PMID 22353646, 2012). "Curtent cilincal trails with inhibitors against CSF-1R in inflammatory diseases and cancer." (PMID 40007537, 2025). "Similarly, the possibility of manipulating Colony-stimulating factor 1 receptor (CSF1R) was viewed as a strategy of reprogramming the macrophages in cancer therapy." (PMID 41227348, 2025).
cancer (continued). "In contrast, immune-related kinases (ZAP70, SYK, ITK, and CSF1R) displayed reduced activity, implicating dampened immune signaling in pathways like PD-L1 Expression and PD-1 Checkpoint in Cancer (hsa05235), T Cell Receptor Signaling (hsa04660), and B Cell Receptor Signaling (WP23)." (PMID 41387887, 2025). "Clinical application of CSF1R-targeted therapies in cancer treatment." (PMID 40821795, 2025). "Both preclinical and clinical studies have shown that targeting the CSF-1/CSF-1R axis can be a promising therapeutic strategy, as using antagonists and mAbs for CSF-1R have great potential to improve the outcome of patients with advanced cancer." (PMID 39003350, 2024). "This analysis suggests that targeting the CSF-1/CSF-1R signaling axis is a promising strategy for cancer treatment, and CSF-1R inhibitors have great potential to improve the prognosis of patients with advanced cancer." (PMID 39403370, 2024). "What advantages does CSF-1R expression provide to cancer cells?" (PMID 38254773, 2024). "In addition, this review covers recent therapeutic strategies, including monoclonal antibodies and small-molecule inhibitors, targeting the CSF-1R and designed to block the pro-oncogenic role of CSF-1R in cancer cells." (PMID 38254773, 2024). "Consequently, the CSF-1 receptor (CSF-1R) has been targeted by small-molecule inhibitors or antibodies in cancer treatments, showing promising effects in vivo." (PMID 39200265, 2024). "Similarly, CSF-1R expression in ECs is poorly studied in both physiology and diseases including cancer." (PMID 39457693, 2024). "This comprehensive approach could ultimately enhance the clinical translation of CSF-1R-targeted treatments and improve patient outcomes across a broader spectrum of cancers." (PMID 39457693, 2024). "As highlighted in a recent review, the CSF-1R is expressed at the cell membrane of cancer cells, where its activation mediates cancer progression through several signaling pathways, thereby promoting proliferation, survival, drug resistance, and the maintenance of cancer stemness." (PMID 39457693, 2024). "Different questions are opened regarding CSF-1R activity and regulation in cancer cells." (PMID 38254773, 2024). "Thus, blocking the CSF-1/CSF-1R signaling axis has emerged as a potential strategy for cancer immunotherapy." (PMID 39403370, 2024). "Targeting CSF-1/CSF-1R is one of the most well-known strategy to inhibit TAMs functions in cancer." (PMID 38554213, 2024). "However, very little is still known regarding CSF-1R expression and downstream signaling mechanisms in cancer cells." (PMID 38254773, 2024). "The colony-stimulating factor-1 receptor (CSF1R/M-CSFR) is a tyrosine kinase receptor (RTKIII) located on the surface of macrophages, which is implicated with aberrant cell signalling and immunomodulation in cancer." (PMID 37711590, 2023). "Thus, targeting the CSF-1/CSF1R pathway appears to represent an attractive therapeutic strategy in the treatment of cancers." (PMID 37143666, 2023). "However, (−)-KU still has a different action on cancer-related proteins when compared with pexidartinib (a potent CSF1R inhibitor)." (PMID 37959760, 2023). "However, limited therapeutic benefit was observed in cancer patients treated with monotherapy, although TAMs were significantly depleted by CSF1R blockade." (PMID 37383234, 2023). "Similar abundance of CSF1R was observed between healthy and tumorous livers from cancer patients." (PMID 36890818, 2023). "To determine the functional contribution of M-CSF and CD155 downregulation to carcinogen-induced cancer cell immunogenicity, we examined whether CSF1R and TIGIT blockade could lead to the rejection of DMBA3-4 + DMSO3-1 tumors in WT mice." (PMID 37843274, 2023).